NOD2 (nucleotide binding oligomerization domain containing 2)
Diseases named in the same sentence as NOD2 in open-access papers (continued):
Sharing a sentence is not in itself a finding about the gene and the disease.
psoriasis (13 papers, 2013 to 2025). An autoimmune condition characterized by red, well-delineated plaques with silvery scales that are usually on the extensor surfaces and scalp. "The NOD2 mutations can cause various conditions such as immune deficiencies, autoimmune and autoinflammatory conditions, and psoriasis." (PMID 39992598, 2025). "Case with psoriasis has homozygous DCLRE1C, heterozygous ZAP70, RFX5, AKT1, and NOD2 gene variants, and all of them were VUS variants." (PMID 39992598, 2025). "The observed association between psoriasis and IBD is well documented and supported by shared genetic and immunologic pathways, including polymorphisms in IL23R, NOD2, and CARD9 genes." (PMID 40746559, 2025). "Subsequently, WGCNA showed the hub genes (e.g., S100A12, CYCS, NOD2, STAT1, HSPA4, AIM2, MAPK7), which were significantly associated with clinical phenotype, PANoptosis signature, and identified immune response in psoriasis." (PMID 38125299, 2024). "Also, AIM2 and NOD2 are key players in pyroptosis (hub genes) identified through our analysis in psoriasis." (PMID 40771724, 2025). "Similarly, miR-192–5p is significantly elevated in the serum of patients with AS and psoriasis, and its overexpression suppresses NOD2 expression." (PMID 39072329, 2024). "Moreover, chronic activation of NOD2 by muramyl dipeptide induces tolerance to bacterial products, and topical treatment with muramyl dipeptide is an effective therapy for psoriasis treatment." (PMID 33925158, 2021). "Although, two missense mutations of NOD2 (R702W, G908R) and one frame-shift mutation Leu1007fsinsC (3020insC) were suggested to be genetic risk factors for psoriasis, there is no clear association of NOD2 genetic variants to the disease." (PMID 33925158, 2021). "In psoriasis the link with the NOD2/CARD15 gene has been excluded." (PMID 23971052, 2013). "Our analysis identified CASP1, CASP5, AIM2, NOD2, GZMB, GZMA, and IL1B as key hub genes in the inflammatory pathways driving psoriasis pathogenesis." (PMID 40771724, 2025). "In this study, we provide a comprehensive analysis of pyroptosis-related genes (PRGs) in psoriasis, identifying key molecular players such as CASP1, CASP5, AIM2, NOD2, and IL1B that drive the inflammatory response and disease progression." (PMID 40771724, 2025). "Keratinocytes respond to naRNA with expression of psoriasis-related genes (e.g., IL17, IL36) via atypical NOD2-RIPK signaling." (PMID 38783164, 2024). "All components required for the activation of inflammasomes are found in keratinocytes of psoriasis lesions, and NLR signaling genes NOD2 and PYCARD are upregulated in psoriasis affected epidermis." (PMID 32922182, 2020). "Upon activation, both AIM2 and NOD2 trigger the formation of inflammasomes that ultimately lead to CASP1 activation, which processes pro-inflammatory cytokines such as IL-1β, which is also a key player in psoriasis through our former analysis." (PMID 40771724, 2025).
Granuloma (12 papers, 2013 to 2025). A compact, organized collection of mature mononuclear phagocytes, which may be but is not necessarily accompanied by accessory features such as necrosis. "We confirm that XIAP deficiency, a cause of monogenic IBD with granuloma, does disrupt NOD2-mediated cytokine production and provide novel evidence that it disturbs NOD2-dependent xenophagy." (PMID 26953272, 2017). "In contrast, biopsies from Crohn’s patients show isolated granulomas with loose lymphocytic borders and sclerosis of surrounding tissue, which are also seen in immunodeficiency disorders, and therefore compatible with loss-of-function variants of NOD2." (PMID 25136265, 2014). "NOD2 variants are also associated with susceptibility to Crohn's disease, characterized by non-caseating granulomas within the gastrointestinal tract." (PMID 36891233, 2023). "The diagnosis of EOS/BS can be supported by the demonstration of non-caseating granulomas within skin, synovial, or conjunctival biopsies, and the presence of NOD2 mutations." (PMID 34682177, 2021). "Thus, even if the therapeutic strategy is to suppress NOD2 expression, if it is effective in preventing inflammatory flare-ups, it may be effective in preventing the maintenance of granulomas as a result." (PMID 37415984, 2023). "No expression of NOD1 or NOD2 was detected in the focal and diffuse paucibacillary lesions, while a strong expression of NOD2 and occasional NOD1 was observed in the multibacillary granulomas." (PMID 40433460, 2025).
Immunodeficiency (12 papers, 2013 to 2025). Failure of the immune system to protect the body adequately from infection, due to the absence or insufficiency of some component process or substance. "Due to NOD2′s complexity and importance, its deficiency, especially in the case of NOD2 mutations, results in exacerbated inflammation and several immune diseases." (PMID 34440800, 2021). "This study helps to provide a comprehensive view of the potential role of inborne errors in the LRR domain of NOD2 on the molecular mechanisms of diseases, errors which may facilitate the development of the associated immune diseases." (PMID 34440800, 2021). "Genetic screening of a patient with immunodeficiency and enteropathy revealed a rare homozygous missense mutation in the first CARD domain of NOD2 (ENST00000300589; c.160G > A, p.E54K)." (PMID 35273242, 2022). "More sequencing data and studies on the mechanism of cancer occurrence and clinical trials about NOD2 gene, such as inflammation and immune disease area, are needed to further reveal the specific mechanism of action in kidney cancer areas." (PMID 29254180, 2017). "On the one hand, monocytes in CD have immune deficiencies such as lack of NOD2‐mediated immune regulation and failure to induce Paneth cell defensins." (PMID 37400975, 2023). "Genes with fine-mapped coding variants, such as NOD2 and TYK2, are also historically known to be responsible for Blau syndrome (dominant) and immunodeficiency (recessive) respectively, suggesting converging biological mechanisms between polygenic and Mendelian immune disorders." (PMID 35041074, 2022). "It is also hypothesized that the inferred immunodeficiency conferred by a defective NOD2 is arguable and that the presence of bacteria or bacterial components in the lamina propria has not been proved to trigger the inflammation in CD." (PMID 25973436, 2015).
lung carcinoma (12 papers, 2012 to 2025). "Mutations in NOD2 result in increased NF-κB activity, a phenomenon observed in various human malignancies such as colorectal, thyroid, breast, and lung cancers." (PMID 40563649, 2025). "Lener's group found that the 3020insC mutation of the NOD2 might be a genetic predisposing factor for aggregations of lung cancer." (PMID 34268854, 2021). "It was also found that polymorphisms of NOD1/CARD4 may affect the diagnosis and treatment of lung cancer, while polymorphisms of NOD2 were also associated with an increased risk of lung cancer." (PMID 34805165, 2021). "The 3020insC variant of the NOD2/CARD15 gene is implicated in the development of chronic inflammation and increased risk of solid tumors such as colorectal, gastric, breast, and lung cancer, as well as non-Hodgkin's lymphoma." (PMID 32596371, 2020). "We incubated HEK-Blue cells expressing human TLR2, TLR3, TLR4, TLR5, TLR7, TLR8, TLR9, or the intracellular PRR protein NOD2 with 100 μg/ml DRibbles derived from the mycoplasma free lung cancer cell line UbiLT3." (PMID 27490927, 2016). "Our results revealed down‐regulated NOD2 in macrophages induced by lung cancer cells could impel the phenotypic conversion of TAMs from the protective M1 phenotype to the pro‐tumorigenic M2 subtype." (PMID 34268854, 2021). "Furthermore, in lung cancer cells, the suppressor of cytokine signaling 3 (SOCS3) mediates in NOD2 ubiquitination, which results in proteasomal decomposition." (PMID 41340462, 2025). "There was an obvious decline in NOD2 expressions in primary lung cancer tissues than those of normal lung tissues." (PMID 34268854, 2021).
colon carcinoma (11 papers, 2013 to 2024). "In this study, we evaluated the function of Nod2 in myeloid cells in a model of acute colitis and colitis-associated colon cancer (CAC)." (PMID 37876927, 2023). "The NOD2 rs2066844 risk allele was associated with a first-degree family history of colon cancer (12.7% vs. 4.7%, p = 0.02)." (PMID 34198814, 2021). "The presence of CCR2 enabled these inducible nonclassical monocytes to infiltrate both intra- and extravascular metastatic sites of melanoma, lung, breast, and colon cancer in murine models, and they reversed the increased susceptibility of Nod2–/– mutant mice to cancer metastasis." (PMID 39545417, 2024). "A recent study had shown a pro‐inflammatory microenvironment in the intestines of both NOD2‐deficient and RIPK2‐deficient increased susceptibility to colon cancer." (PMID 34268854, 2021). "In addition to upregulating PD-L1, L. mesenteroides also activated Toll-like receptors (TLRs) and NOD-like receptors (NODs) pathways, specifically through TLR2 and NOD2, while also exerting a suppressive effect on autophagy in colon cancer cell lines." (PMID 38755413, 2024). "miR-192 also benefits the prognosis of colon cancer patients by regulating SRPX2, Rab-2A, RhoA-ROCK-LIMK2, farnesoid X receptor, RB1/E2F1 pathway, and NOD2." (PMID 33614788, 2021). "Among our CD patients, carriers of the NOD2 SNP rs2066844 had significantly more often first-degree relatives with colon cancer than non-carriers." (PMID 34198814, 2021). "Analysis of THP1 human monocytic cells or HCT-116 human colon carcinoma cells, which both express NOD2 endogenously, confirmed that CYLD was not involved in controlling Met1-Ub accumulation on HOIP whereas OTULIN was indispensable." (PMID 26997266, 2016). "The complete selectivity of GSK669 and GSK400 towards inhibition of NOD2 but not NOD1-mediated IL-8 secretion was also evident in HCT116 colon carcinoma cells which endogenously express both NOD1 and NOD2." (PMID 23936340, 2013).
dermatitis (11 papers, 2011 to 2024). An inflammatory process affecting the skin. "Diagnostically challenging patients with the following clinical and genetic characteristics were prospectively studied between January 2009 and April 2011: periodic fever, dermatitis, polyarthritis, serositis, negative serum autoantibodies and additional positive NOD2 IVS8+158 gene mutation." (PMID 21914217, 2011).
glioma (11 papers, 2014 to 2025). A benign or malignant brain and spinal cord tumor that arises from glial cells (astrocytes, oligodendrocytes, ependymal cells). "Previously, a prognostic model comprising three PRGs (CASP4, CASP9, and NOD2 (encoding nucleotide binding oligomerization domain containing 2)) was constructed to predict the outcomes of patients with glioma." (PMID 36119521, 2022). "NOD2 protein expression was validated in glioma cell lines using Western blot and immunofluorescence analyses." (PMID 40868292, 2025). "Lentivirus-based NOD2 knockdown in human foreskin fibroblasts (HFFs) and U373 glioma cells leads to enhanced HCMV replication along with decreased levels of interferon beta (IFN-β) and the pro-inflammatory cytokine, IL8." (PMID 24671169, 2014). "All tested glioma cell lines demonstrated robust NOD2 expression." (PMID 40868292, 2025). "Similarly, infection of U373 glioma cells with Towne HCMV resulted in significant upregulation of NOD2 at 72 hpi." (PMID 24671169, 2014). "In this study, we comprehensively investigated NOD2’s role in GBM progression through the bioinformatics analysis of clinical datasets and functional characterization in glioma cell lines." (PMID 40868292, 2025). "TCGA glioma cohort analysis and RT-qPCR results showed that PLCG1 transcription was significantly decreased, while NOD2 transcription was elevated in patients with GBM compared with patients with LGG." (PMID 40761791, 2025). "Furthermore, the expression levels of genes encoding NLR proteins (NLRP12, NOD2, NOD1, NLRC4, and NAIP), inflammasome adaptor molecules (PYCARD), and proinflammatory caspases (CASP1, CASP4, and CASP5) were significantly higher in glioma patients than in normal controls." (PMID 31133717, 2019).
hepatocellular carcinoma (11 papers, 2020 to 2025). A malignant tumor that arises from hepatocytes. "Furthermore, NOD2 has been observed to enhance the susceptibility of hepatocellular carcinoma to chemotherapy through its targeting of the AMPK pathway and subsequent tumor inhibition." (PMID 38312660, 2024). "Thus, our data demonstrate that the innate immunity gene Nod2 protects mice from the altered expression of genes associated with the development of cancer, liver hyperplasia, liver carcinoma, and inflammation in the DMBA + HFD model of liver cancer." (PMID 33239685, 2020). "In hepatocellular carcinoma, NOD2 activates AMPK, MAPK, NF-κB, STAT3, and ERK pathways and induces nuclear autophagy directly through Lamin A/C." (PMID 39353904, 2024). "NOD2 also promoted hepatocellular carcinoma development through DNA damage-induced autophagy mechanism." (PMID 39353904, 2024). "The study of hepatocellular carcinoma indicates that NOD2 is an innate immune sensor initiates the immune response against pathogens, and acted as a tumor suppressor by directly activating AMPK pathway." (PMID 35574984, 2022). "NOD2 expression was measured in clinical hepatocellular carcinoma (HCC) samples using qPCR (80 pairs), western blotting (30 pairs) and immunostaining (141 pairs)." (PMID 33413510, 2021). "Genes involved in the biosynthesis of asparagine (Asns) and serine (Phgdh) and in folate metabolism (Mthfd1l and Mthfd2) were also elevated in Nod2−/− DMBA + HFD mice and are associated with the development of hepatocellular carcinoma." (PMID 33239685, 2020). "Recently, Nod2 was shown to protect from the development of hepatocellular carcinoma (HCC) using N-nitrosodiethylamine (DEN)/carbon tetrachloride (CCl4) and xenograft tumor animal models." (PMID 33239685, 2020). "For example, PRSS12 in Panc-AdenoCA, ABCC11 in liver hepatocellular carcinoma (Liver-HCC), and NOD2 in skin melanomas (Skin-Melanoma) show tissue-specific expression patterns." (PMID 38143269, 2023). "We demonstrate that Nod2−/− mice treated with DMBA and maintained on HFD for 31 weeks had altered expression of genes in pathways associated with the development of cancer, liver hyperplasia, liver carcinoma, liver steatosis, hepatocellular carcinoma, inflammation, and cholesterol biosynthesis." (PMID 33239685, 2020). "Here we investigated the role of NOD2 in the development of hepatocellular carcinoma (HCC)." (PMID 32144252, 2020). "Interestingly, NOD2’s role in cancer appears context-dependent, as evidenced by reports showing that NOD2 can inhibit tumorigenesis and enhance therapeutic efficacy through the AMPK pathway in hepatocellular cancer." (PMID 40868292, 2025).
melanoma (11 papers, 2011 to 2025). A malignant, usually aggressive tumor composed of atypical, neoplastic melanocytes. "In a widely used model of hematogenous metastasis in which syngeneic B16F10 melanoma cells are injected i.v. or retro-orbitally, deficiency of Nod2 dramatically increased tumor metastasis to the lung and other sites, such as the liver." (PMID 39545417, 2024). "In Poland, the association with the NOD2 polymorphism and rectal; gastric, prostate, thyroid, melanoma; pancreatic; breast and ovarian cancers was not confirmed." (PMID 35478773, 2022). "This study aimed to investigate these function of NOD2 in melanoma and its underlying mechanisms." (PMID 39353904, 2024). "In all four databases investigated, NOD2 expression appears strongly and significantly reduced in melanoma patients, suggesting that the loss of its beneficial function in the immune and autoimmune surveillance may have a role in melanoma." (PMID 35205739, 2022). "have been shown to enhance responses to chemotherapy and ICB in mouse melanoma models by secreting SagA, which hydrolyzes bacterial peptidoglycans to create muropeptides that activate NOD2 signaling in macrophages, triggering immune activation." (PMID 40264971, 2025). "Nod2–/– and Nr4a1–/–Nod2–/– double-mutant mice showed a pronounced increase in tumor seeding and progression of melanoma metastasis in the lungs compared with Nr4a1–/– and WT mice." (PMID 39545417, 2024). "NOD2 inhibited the proliferation of melanoma cells, hindering their migration and invasion while promoting the onset of apoptosis." (PMID 39353904, 2024). "In this study, we investigated the role of NOD2 in melanoma, and the results showed that NOD2 has a protective function." (PMID 39353904, 2024). "We found more extravascular B16F10 melanoma cells in Nod2–/– or Nr4a1–/– than in WT mice, indicating increased engraftment." (PMID 39545417, 2024). "The findings indicated that NOD2 overexpression suppressed melanoma cell migration and invasion, whereas NOD2 knockdown increased these abilities." (PMID 39353904, 2024). "By upregulating NOD2 expression, we successfully inhibited melanoma growth and confirmed that NOD2 diminished melanoma ability to resist chemotherapeutic drugs by reducing TYMS level and activity." (PMID 39353904, 2024). "We also used another NOD2 knockdown sequence (sh-NOD2-1) of A875 cells injected subcutaneously into nude mice to reconfirm the promotional effect of NOD2 knockdown on melanoma cell growth in vivo." (PMID 39353904, 2024). "Reconstitution of Nod2–/– mice with a pure cell population of I-NCMs prior to injection of B16F10-LUC2 melanoma cells suppressed new pulmonary B16 melanoma metastasis." (PMID 39545417, 2024). "While most of the previous studies focused on the immunomodulatory role of NOD2, the present study analyzed its protective role in melanoma from a genetic perspective." (PMID 39353904, 2024). "Melanoma cells and an in vivo model of sh-NOD2-1, we reconfirmed that NOD2 knockdown upregulated the protein levels of TYMS, PLK1, and p-PLK1." (PMID 39353904, 2024). "In investigating the effect of NOD2 on apoptosis in melanoma cells, flow cytometry assays demonstrated that NOD2 overexpression increased the apoptosis rate, while NOD2 knockdown decreased it." (PMID 39353904, 2024). "Our findings are consistent with previous studies, which reported that a combination of NOD2 agonists with interferon and tumor microparticle vaccine activated NOD2 signaling, generated an anti-tumor immune response, and inhibited melanoma growth." (PMID 39353904, 2024). "In this study, we found that NOD2 negatively regulated TYMS expression and activity in melanoma and promoted its K48-linked ubiquitination, thereby enhancing the degradation of TYMS through the ubiquitin-proteasome system." (PMID 39353904, 2024).